CDKN2B (cyclin dependent kinase inhibitor 2B)
Diseases named in the same sentence as CDKN2B in open-access papers (continued):
Sharing a sentence is not in itself a finding about the gene and the disease.
cancer (200 papers, 2006 to 2026). A tumor composed of atypical neoplastic, often pleomorphic cells that invade other tissues. "Regarding CDK4/6 inhibitors, somatic mutations in CDK 4 inhibitor B (CDKN2B) were associated with an increased risk of cancer-associated VTE, suggesting a potential pathophysiological link between CDK4/6-inhibiton and thrombotic risk." (PMID 40896464, 2025). "CDKN2B is a cell cycle inhibitor that can cause proliferative cell states when deleted or mutated in a multitude of cancer types." (PMID 40585242, 2025). "As typical tumor suppressor genes (TSGs), the cyclin‐dependent kinase inhibitors CDKN2A and CDKN2B located on chromosome 9, band p21.3, are frequently mutated, deleted, or dysregulated in a variety of cancers." (PMID 35253368, 2022). "So far, there are a few mechanistic models were proposed to explain the loss of CDKN2B/p15INK4b expression in human diseases, especially in cancers." (PMID 33664859, 2021). "As for CNV loss, deletion of CDKN2A/CDKN2B on chromosome 9 was associated with multiple drugs in multiple cancer types." (PMID 33741950, 2021). "LncRNA CDKN2B-HS1 can recruit the Suz12 subunit of PRC complexes and CBX7 subunit of PRC1 complexes to combine with the H3K27 modification locus and mediate the suppression of the expression of cancer associated CDKN2A/CDKN2B genes." (PMID 29292750, 2017). "The loss of CDKN2A and CDKN2B was observed in various cancers through deletion, inactivating mutations, epigenetic silencing or post-translational modification." (PMID 29156722, 2017). "Genomic locus at chromosome 9p21 that contains the CDKN2A and CDKN2B tumor suppressor genes is inactivated through mutations, deletions and promoter methylation in multiple human cancers." (PMID 26909863, 2016). "This situation contrasts with the emerging information related to the risk mechanisms at 9p21.3, where the function of one likely causal gene CDKN2B is associated with decreased risk for vascular disease as well as a broad range of human cancers." (PMID 23874238, 2013). "The p16/p15 proteins encoded by CDKN2A/CDKN2B are known to be associated with telomerase activation and cancer progression as well as to induce cell cycle arrest by inhibition of CDK4 kinase." (PMID 18652687, 2008). "Moreover, some genes (particularly CDKN2B) that are significantly and consistently related with cancer are also associated with PD, which suggests shared genetic susceptibility between the two diseases." (PMID 32626518, 2020). "In a clinical study, a genetic variant of CDKN2B had an increased risk of cancer susceptibility." (PMID 31215439, 2019). "Loss of CDKN2B is a very frequent event in several cancers, including PC." (PMID 27486767, 2016). "Loss of p15INK4b function and CDKN2B mutations has been described in several types of tumors confirming that the inactivation of p15INK4b significantly contributes to the transformation of normal cells into cancer cells." (PMID 26121660, 2015). "One of the most common sporadic homozygous deletions in cancers is 9p21 loss, which includes the genes methylthioadenosine phosphorylase (MTAP), CDKN2A, and CDKN2B, and has been correlated with worsened outcomes and immunotherapy resistance." (PMID 38330461, 2024). "Genomic profiles of cancer patients identified that tumor-induced mutations in KRAS, STK11, KEAP1, CDKN2B, CTNNB1, and MET are significantly associated with cancer-associated thrombosis." (PMID 37046748, 2023). "Mutations in STK11, CDKN2B, KEAP1, CTNNB1, MET, and KRAS were associated with a significantly increased risk of cancer-associated thrombosis." (PMID 38069251, 2023). "LncRNA CDKN2B anti-sense RNA 1 (CDKN2B-AS1), which is an anti-sense RNA of cyclin-dependent kinase inhibitor 2B (CDKN2B), plays an important role in many diseases, including cancer." (PMID 35409396, 2022).
cancer (continued). "This region contains 46 annotated genes and loci including the known cancer-associated cyclin-dependent kinase inhibitor encoding genes CDKN2A and CDKN2B." (PMID 34946912, 2021). "In these DEGs, several cancer‐associated genes such as HOXC10, THBS1, CDKN2B, PAX2 and H19 were significantly associated with AML biology." (PMID 31794134, 2020). "The TGF-β cytostatic program in epithelial cells involves, among other molecular events, the induction of Cdkn1a and Cdkn2b but cancer cells utilize any opportunity to circumvent TGF-β ability to inhibit cell proliferation." (PMID 31036808, 2019). "The INK4b-ARF-INK4a locus is believed to be regulated by Polycomb repressive complexes, and CDKN2B expression is frequently down-regulated in cancers." (PMID 30266084, 2018). "The expression levels of CDKN2B/P15 protein in cancer tissue samples of VER responsive (CR, 12 cases) and unresponsive groups (PD, 10 cases) were tested using immunohistochemistry." (PMID 29299129, 2017). "CDKN2A and CDKN2B are inactivated in a number of different cancers, and mono- or biallelic deletion of CDKN2A are recurrent events in childhood ALL7." (PMID 26463672, 2015). "In cancers that have genomic driver insults in CDKN2A or CDKN2B, inhibition of CDK4/6 is likely to be a therapeutic option worth investigating." (PMID 26634163, 2015). "Many genes in this region (e.g., the CDKN2A/CDKN2B locus and MTAP) were found to be associated with different types of cancer." (PMID 25522020, 2014). "The INK4a/ARF/INK4b locus (also known as CDKN2A and CDKN2B) plays a pivotal role in aging and cancer." (PMID 21347436, 2011). "Methylation of CDKN2B or the p15 tumor suppressor gene is frequently reported in myeloid malignancies." (PMID 21760961, 2011). "These have mostly involved cancer phenotypes because the cell-cycle regulators CDKN2A and CDKN2B are recognised to be involved in predisposition to certain cancers." (PMID 20386740, 2010). "CDKN2B deletion was the most recurrent CNA across all cancer types." (PMID 41537310, 2026). "While Cdkn3 is expressed mostly in cancer, other CDKIs are categorized into the Cip/Kip family (p21 encoded by cdkn1a, p27/cdkn1b, and p57/cdkn1c) and INK4 family (p16/cdkn2a, p15/cdkn2b, p18/cdkn2c, and p19/cdkn2d)." (PMID 39668249, 2025). "When considering all cancer types, pathogenic somatic variants in CDKN2A (identified in 12%.7 of CFTR PV carriers; Sidak‐corrected p = 0.0069) and CDKN2B (identified in 4.2% of CFTR PV carriers; Sidak p = 0.0428) were more common in our cohort of CFTR PV carriers than in the global COSMIC database." (PMID 41147257, 2025). "In a previous study, next-generation sequencing (NGS) was used for mapping CCA, 182 cancer-associated genes and 37 introns were identified from 14 cancer-rearranged genes, which demonstrated that biliary tract tumors share the same chromatin remodeling (ARID1A) and genomic aberrations (CDKN2B)." (PMID 36936931, 2023). "In a previous study where next-generation sequencing (NGS) was used for mapping CCA, 182 cancer-associated genes and 37 introns were identified from 14 cancer-rearranged genes, which demonstrated that biliary tract tumors share the same chromatin remodeling (ARID1A) and genomic aberrations (CDKN2B)." (PMID 37954763, 2023). "This suggests that CDKN2A and CDKN2B play an important role in certain cancer types." (PMID 35253368, 2022).
cancer (continued). "Furthermore, our results are confirmed by the literatures, with 6 out of top 10 features associated with specific cancers including NKIRAS1, CDKN2B, YTHDC2, MECOM, RBFOX1, and RAB6B." (PMID 33329723, 2020). "In addition, qPCR analysis confirmed homozygous deletions of Cdkn2a and Cdkn2b, another common deletion present in multiple human cancers." (PMID 29925311, 2018). "CDKN2B/P15 protein was mainly expressed in the nucleus and cytoplasm of cancer cells." (PMID 29299129, 2017). "The viewpoint that CDKN2B methylation may lead to unlimited cell proliferation has been verified in a spectrum of cancers." (PMID 27905995, 2016). "Our results suggest that the cell-type specific depleted signals in cancer cell lines may be under genomic alterations and can be located near genes associated with different types of cancer (i.e. FHIT, STK11, CDKN2A, CDKN2B)." (PMID 25522020, 2014). "However, it is possible that the genomic plasticity of CDKN2B observed here is connected with the rather high frequency of cancers in the domestic dog." (PMID 19643034, 2009). "Similarly, EdU results revealed that silencing of KLF2 and CDKN2B could partially rescue SNHG1 knockdown induced reductions in cancer cell proliferative capacity." (PMID 30266084, 2018). "However the role of Arnt in regulation of CDKN2B in these cancer types remains to be examined." (PMID 24618291, 2014). "Some genes, such as CDKN2B and CCNA1, exhibited inconsistent expression patterns across different cancer types, suggesting dynamic expression across tissues." (PMID 40149461, 2025). "Changing the CDKN2B gene, which is vulnerable to several significant human diseases, including CVD and cancer, is mediated through expression." (PMID 40900941, 2025). "LEF1, WT1 and BCL11B copy number abnormalities were reported from the TARGET study of 2471 pediatric cancer patients whereas in our group we found CDKN2A, CDKN2B and MTAP harboring most copy number variations." (PMID 38459434, 2024). "The 9p21.3 region, which contains the three tumor suppressor genes CDKN2A, CDKN2B and MTAP, is known to be frequently deleted in different types of cancer cells." (PMID 36762651, 2023). "Next, we analyzed the correlation between MIR31HG expression and the deletion of these three genes (CDKN2A, CDKN2B, and MTAP) in 807 cancer cell lines from the CCLE database." (PMID 35570408, 2022). "Cyclin-dependent kinase inhibitors: The family of cyclin-dependent kinase inhibitor genes, CDKN2A (p16-INK4), CDKN2B (p15-INK4b), CDKN2C (p18-INK4c), and CDKN2D (p19-INK4d), are tumor suppressor genes generally inactivated in human cancers." (PMID 35056738, 2022). "CDKN2B (also named INK4B), a key cell cycle inhibitor, is related to the cell cycle and TGF-beta signaling pathway in cancer." (PMID 31215439, 2019). "Based on previous studies, miR-31has been recognized as a potent cancer-related miRNA,involved in carcinogenesis of CRC by targeting tumorsuppressor genes such as HIF-1a and CDKN2B." (PMID 29633600, 2018). "p16INK4A/CDKN2A and p15INK4B/CDKN2B, which are CDKIs for CDK4/6, are downregulated in several types of cancer." (PMID 28931650, 2017). "Recently, many epigenetic biomarkers have been studied in cancer diagnosis, including hMLH1, E-cadherin, CDKN2A, CDKN2B and APC in GC and SEPT9, SFRP2, THBD, SDC2, VIM and FBN1 in CRC." (PMID 29137404, 2017).
cancer (continued). "The associations of the deletion of tumor suppressor genes CDKN2A, CDKN2B, and MTAP with the four significant enriched cancer types in this subgroup have been widely investigated and reported." (PMID 26148869, 2015). "TBX2 and its close relative, TBX3, negatively regulate cell cycle control genes and CDKNs, specifically CDKN2A, CDKN2B, and CDKN1A and are often upregulated in several cancers." (PMID 22829758, 2012). "Due to the fact that CDKN2B is almost always deleted together with CDKN2A in human cancer, it has not received sufficient scientific interest." (PMID 38561743, 2024). "CDKN2B, also known as P15, belongs to the INK4 family, which has been identified as an inhibitor of cyclin-dependent kinase 4, thus inhibiting cell cycle progression and facilitating cell apoptosis in a variety of human cancers." (PMID 36776317, 2023). "Notably, the specific HCGs shared by both cancer cell lines included CDKN2A, CDKN2B, and MTAP deletions on chromosome 9 and RRAS2 insertions on chromosome 11." (PMID 35570408, 2022). "The expression of CDKN2A, CDKN2B, CDKN2C, and CDKN2D was positively correlated with the T stage, and the expression of CDKN2A, CDKN2B, and CDKN2C was positively correlated with the pathological stage, indicating that patients with more advanced cancer tended to express higher mRNA levels of INK4." (PMID 35771229, 2022). "The expression of CDKN2A, CDKN2B, CDKN2C, and CDKN2D was analyzed in 20 types of cancers." (PMID 35771229, 2022). "The principle CDK4/6 inhibitors lost in cancer are CDKN2A and CDKN2B." (PMID 32242058, 2020). "Notably, the expression of the MIZ1 target genes Cdkn1a, Cdkn2a, and Cdkn2b, known to be repressed by MYC–MIZ1 complexes in cancer cells, were also similar between the LZ of MycVD and MycWT." (PMID 32407433, 2020). "Among them, 9p21.3 was the only region that covers cancer-related genes, CDKN2A and CDKN2B." (PMID 31235699, 2019). "Mutual exclusivity analysis with genomic alteration data showed that STK11 alterations in cancer patients rarely co-occur with CDK4, CDKN2A, CDKN2B or RB1, supporting a role for STK11 in an oncogenic pathway that is intimately associated with cell cycle function." (PMID 28205554, 2017). "Gene array profiles showed that the genes related to antiproliferative pathway were upregulated, such as GTP-binding RAS-like 3 (DIRAS3), retinoblastoma-like 1 (Rbl-1), and cyclin-dependent kinase inhibitor 2B transcript (CDKN2B), but different genes were modulated in various cancer cell lines." (PMID 28377788, 2017). "Additionally, two other well-known recessive cancer genes, CDKN2A and CDKN2B, also had significant p-values, albeit lower rankings (p<0.0025 and FDR = 0.019, respectively)." (PMID 18846217, 2008). "Cell cycle, cancer and cell morphology are the top functions influenced by genes in Network A. Sixteen genes differentially expressed between NC and CIN III are involved in this network including RBL2/p130, SMARCC1, NCOR1, PTEN, DHFR and CDKN2B." (PMID 18248679, 2008). "Therefore, we assume that CDKN2A/CDKN2B aberrations reflect a general mechanism of cancer rather than a specific prognostic group of children with T-ALL." (PMID 38783324, 2024). "However, the role of the CDKN2B gene in cancer progression has not been well defined because of CDKN2B inactivation." (PMID 33664859, 2021). "Although this study was limited to U2OS cells, we envision that the interaction between Miz-1 and Arnt might be of importance in cell cycle progression in other cancer cells, however not necessarily for the regulation of CDKN2B." (PMID 24618291, 2014). "However, hypermethylation of CDKN2B has not been frequently reported in cancers." (PMID 28600574, 2017).
cancer (continued). "Second, there were cases in TCGA tumors and CCLC cancer cell lines in which JAK2 was deleted in the absence of CDKN2A/CDKN2B or PTPRD deletion, suggesting that JAK2 deletion alone may have a functional benefit to cancer cells." (PMID 28977839, 2017). "Indeed, as proof of the validity of our method, we identified many genes that are known to be differentially methylated across various cancer types (CDKN2A, CDKN2B, MGMT, SFRP1), in addition to many novel genes not previously known to be regulated by DNA methylation." (PMID 25486910, 2014).
cardiovascular disease (5 papers, 2012 to 2025). "One interesting region associated with type 2 diabetes (T2D) and cardiovascular disease (CVD) is on chromosome 9p21 in a gene desert ~130 kb upstream of CDKN2B." (PMID 26089876, 2015).
CNS tumors (4 papers, 2019 to 2024). "Among CNS tumors, gains and losses were distributed throughout the genome with some chromosome arms having a higher rate of either gain (7q, 8q, 12q) or loss (9p, specifically CDKN1A and CDKN2B)." (PMID 31133068, 2019).
hematologic malignancies (2 papers, 2012 to 2024). "We focused primarily on the genomic region of chromosome 9p21 since this region containing cdkn2a and cdkn2b is known to be deleted in multiple solid and hematologic malignancies." (PMID 22948084, 2012).
kidney disease (1 paper, 2022). "However, to our knowledge, no prior studies have shown CDKN2B or CCND1 eQTLs associating with kidney disease, as described in this manuscript." (PMID 35730565, 2022).
metabolic disorders (1 paper, 2017). "Notably, four of seven methylation loci were located in coding genes (ANK3, CDKN2B, CACNA1G) and the miRNA let-7b host gene (MIRLET7BHG) that have been previously implicated in metabolic disorders in human adults and animal model systems." (PMID 28264723, 2017).
CDKN2B also shares sentences with these, for which no sentence is quoted: prostate carcinoma (11 papers); liver cancer (6); non-small cell lung carcinoma (4); angiosarcoma (3); dysplastic nevi (3); oligodendroglioma (3); syphilis (3); anaplastic astrocytoma (2); aortic aneurysm (2); B-cell acute lymphoblastic leukemia (2); cardiac hypertrophy (2); childhood cancer (2); chronic lymphocytic leukemia (2); Ewing sarcoma (2); follicular thyroid carcinoma (2); genetic disorders (2); head and neck squamous cell carcinoma (2); infection (2); invasive breast carcinoma (2); Liver Disease (2); malignant rhabdoid tumor (2); monoclonal gammopathy of undetermined significance (2); myxofibrosarcoma (2); neuroblastoma (2); pleural mesothelioma (2); prostate tumor (2); renal fibrosis (2); squamous cell carcinoma (2); adenocarcinoma (1); alcoholic liver diseases (1).
A further 77 diseases each share a sentence with CDKN2B in 1 paper.